CENPA (centromere protein A)
Diseases named in the same sentence as CENPA in open-access papers (continued):
Sharing a sentence is not in itself a finding about the gene and the disease.
cancer (continued). "Assessment of CENPA expression was also examined in cancer cell line models to determine feasibility for more focused molecular inquiry." (PMID 32371391, 2020). "The top activated transcriptional regulators were CENPA, FOXM1, TCF24, and MYBL2, which were linked to 875, 845, 843, and 840 cancer-specific enhancer probes, respectively." (PMID 32925947, 2020). "Centromere protein-A (CENPA) is a histone-H3 variant that regulates cell division and has been associated with cancer progression." (PMID 32090070, 2020). "Overexpression of CENPA is observed ubiquitously across various cancers, with evidence of ectopic CENPA deposition at extra-centromeric loci across the human genome." (PMID 31375789, 2019). "The modules significantly contained the nodes (i.e., CENPA, CENPN, and CENPH) which are associated with different cancers and disease progression." (PMID 30658502, 2019). "We found that TOP2A, TTK, CHEK1, and CENPA play critical roles in biological processes that are highly correlated with cancer, such as DNA topological structure, cell cycle progression, and mitosis, thereby suggesting their possible role in cancer development." (PMID 30886771, 2019). "It has been reported that ESCO2, CDCA2 and CENPA are cell cycle-related genes involved in cancer progression." (PMID 29642861, 2018). "In addition, single-gene pan-cancer studies have also inspired us, such as the discovery of the broad diagnostic and prognostic value of RAD51, TRPM7, and CENPA in pan-cancer." (PMID 40108724, 2025). "To explore the cell populations and cellular locations where CENPA is expressed, we conducted an analysis of single-cell sequencing data and observed the subcellular distribution of CENPA through immunofluorescence staining in three cancer cell lines." (PMID 39820192, 2025). "The gene alteration analysis in this study indicated that CENPA mutations are unlikely to be a major driving factor in cancer development, given the low mutation rate observed." (PMID 39820192, 2025). "This comparison indicated that CENPA was significantly overexpressed in 16 cancer types." (PMID 39820192, 2025). "This suggests that cancer cells undergo more frequent cell divisions and, therefore, might require higher levels of CENPA for proper kinetochore regulation." (PMID 39820192, 2025). "This study also aimed to explore the prognostic value of CENPA in various cancers." (PMID 39820192, 2025). "Previous studies have reported the involvement of CENPA in a few cancer types." (PMID 39820192, 2025). "Additionally, we used computational methods to screen and predict potential drugs targeting CENPA in cancer cells." (PMID 39820192, 2025). "Therefore, this study aimed to systematically investigate CENPA in multiple cancer types, regarding the potential of CENPA as a pan-cancer biomarker." (PMID 39820192, 2025). "To test this hypothesis, we examined CENPA expression across several single-cell cancer datasets and compared it with single-cell signals of the G2/M checkpoint, a hallmark gene set related to cell proliferation in GSEA." (PMID 39820192, 2025). "Additionally, common lymphoid progenitors showed a positive correlation with CENPA in most cancer types." (PMID 39820192, 2025). "Furthermore, drugs targeting CENPA in cancer cells were identified and predicted using drug sensitivity correlations and protein-ligand docking." (PMID 39820192, 2025). "Using cross‐genes between cancer functional states subtypes, we constructed a prediction model with 101 prediction models based on machine learning, screening out five oncogenes and further experiments confirmed centromere protein A (CENPA)." (PMID 39620895, 2024). "CENPA has previously been discovered to play a role in malignant tumor progression." (PMID 37928273, 2023). "As with CENPA, TIMP1 was associated with poor prognosis in most cancers." (PMID 37213288, 2023).
cancer (continued). "In light of those findings, it was speculated that NRMT may regulate the CENPA/Myc/Bcl2 axis to affect the chemoresistance in human cancers." (PMID 35013138, 2022). "CENPA overexpression promotes aneuploidy and correlates with a poor prognosis in human cancers." (PMID 36589226, 2022). "Higher expression of CENPA was correlated with increased invasiveness and higher-grade cancers." (PMID 35518784, 2022). "There is evidence that CDC20, TTK, and CENPA were expressed and active in several types of cancer." (PMID 36213834, 2022). "CENPA overexpression is often found to be in different types of cancer, but its mechanism is largely unknown." (PMID 36291764, 2022). "Indeed, the upregulation of CENP-A strongly correlates with the expression of FOXM1 across many cancers and FOXM1 displays at least 100-fold relative enrichment at the CENPA promoter in cancer tissues compared with normal tissues." (PMID 35721491, 2022). "CENPA is highly expressed in human cancer genome and also identified as a regulator of RB protein." (PMID 35013138, 2022). "Thereafter, CENPA levels between the paired PRCC and matched non-carcinoma samples were analyzed by Wilcoxon rank-sum test, while the relations of clinicopathological characteristics with CENPA level were examined by logistic regression and Wilcoxon rank-sum test." (PMID 36163007, 2022). "CENPA expression level is a potential biomarker of poor prognosis in cancer patients." (PMID 34966575, 2021). "The prognostic value of CENPA in human cancers was partly illustrated." (PMID 32337237, 2020). "Given the ubiquitous nature of CENPA overexpression in cancer, it is conceivable that ectopically bound CENPA driving proliferation through transcriptional regulation is a generalizable feature exhibited across numerous cancer types." (PMID 32371391, 2020). "Tumor samples with higher expression of CENPA, FOXM1, and MYBL2 appear to harbor relatively more cancer-specific enhancers, suggesting that tumors highly expressing CENPA, FOXM1, and MYBL2 may have distinct enhancer profiles." (PMID 32925947, 2020). "In order to analyze the cancer more accurately, in our study, we integrated the TCGA database, using bioinformatics analyses to explore likely molecular mechanisms and novel biomarkers in ChRCC and identify CENPA was a vital gene involved in ChRCC." (PMID 32090070, 2020). "CENPA-directed ChIP was additionally conducted in the benign prostatic epithelial cell line 957E-hTERT to determine whether ectopic CENPA binding is a cancer-specific observation." (PMID 32371391, 2020). "In addition, inhibition of CENPA expression in cancer cells can reduce sphere forming ability, proliferation, and cell viability." (PMID 30886771, 2019). "The prognostic significance of CENPA was described for various cancers." (PMID 26587348, 2015). "A mechanism for explaining the generation of aneuploidy could involve mislocalization of CENPA, leading to the genome instability observed during cancer progression." (PMID 20119530, 2009). "Although the function of CENPA in cell growth and cell cycle has been studied, the association of CENPA and cancers has not been studied comprehensively and the clinical use of CENPA as a biomarker for cancer has not been developed." (PMID 39820192, 2025). "However, changes in copy number could potentially influence cancer progression by increasing the transcription of CENPA mRNA." (PMID 39820192, 2025). "Overall pan-cancer data indicated that CENPA copy number could influence mRNA expression." (PMID 39820192, 2025). "In addition, CENPA is significantly correlated with the infiltration of several immune cells, mainly including Th2/1 CD4 + T cells, stroma-score and cancer- associated fibroblast." (PMID 40804263, 2025).
cancer (continued). "However, using antibodies against β‐catenin phosphorylation sites at serine 675 and 552, we observed a significant decrease in protein levels at these sites, suggesting that CENPA may promote cancer by affecting the phosphorylation of β‐catenin protein." (PMID 39620895, 2024). "Moreover, to explore how CENPA might affect cancer pathogenesis, we used the CancerSEA single-cell database to analyze the correlation between CENPA and 14 distinct functions." (PMID 38681202, 2024). "CENPA may regulate cancer by mediating proliferation, DNA repair, and the cycle of GBM cells." (PMID 38681202, 2024). "Importantly, CENPA overexpression has been identified in many cancers." (PMID 38681202, 2024). "Developing selective drugs targeting CENPA may be a promising direction for cancer treatment." (PMID 34627268, 2021). "Interestingly, High-level CENPA in ccRCC is consistent with the CIN in cancer." (PMID 34627268, 2021). "CENPA is not the only H3 variant whose levels and deposition pattern are altered in cancer." (PMID 33167489, 2020). "The centromeric H3 variant CENPA and its cognate chaperone HJURP are overexpressed, usually in a mutually exclusive fashion, in several cancer types including lung, colon, prostate, breast, and brain tumors, where their overexpression correlates with poor prognosis." (PMID 33167489, 2020). "Taken together, these data suggest that CENPA might serve as a tumor marker in cancers." (PMID 26587348, 2015). "Thus, targeting the specific N-terminal domain of CENPA potentially could be used to interfere with the high growth activity of cancer cells." (PMID 20119530, 2009). "The results revealed that almost all cancer types overexpressed CENPA, with the exception of LAML, which exhibited lower CENPA expression in cancerous tissues than in normal tissues." (PMID 39820192, 2025). "Therefore, while CENPA gene mutations may not be the primary driver in most cancers, its copy number alterations might influence cancer development through changes in mRNA expression." (PMID 39820192, 2025). "To explore the mechanism of CENPA's influence on cancer, we searched for EZH2 as an upstream factor of CENPA." (PMID 39620895, 2024). "CENPA and TIMP1 are highly expressed in the tumor tissue of most cancers, while MYCN is usually lowly expressed." (PMID 37213288, 2023). "This suggests that although some cancer-specific enhancers are common to LUAD and BRCA, the enhancers regulated by CENPA, FOXM1, and MYBL2 are largely different between tumor types." (PMID 32925947, 2020). "Here we showed that CENPA, FOXM1, and MYBL2 are upregulated together, potentially leading to the activation of many cancer-specific enhancers in a subgroup of LUAD." (PMID 32925947, 2020). "We further analyzed the differential expression of DPYSL4, HOMER1, ABCB6, CENPA, CDK1, STMN1 in cancer and adjacent tissues, and found that compared with adjacent tissues, the six genes in 309 HCC tissues were significantly up-regulated (P<0.01)." (PMID 31790363, 2019). "For example centromere protein A (CENPA), is involved in cell division and is functionally related to several genes involved in GBM and cancer in general." (PMID 26295306, 2015).
cancer (continued). "The human lung tissue QRT-PCR array assay of 24 paired mRNA samples of cancer and adjacent normal lung tissues was used to validate two AC discriminating genes SPP1 and CENPA." (PMID 22369099, 2011). "Despite its importance, a comprehensive pan-cancer bioinformatic analysis of CENPA has not yet been conducted." (PMID 39820192, 2025). "Most of these studies were also using TCGA data, but they were only limited to one cancer type regardless of the common roles of CENPA across multiple cancer types." (PMID 39820192, 2025). "Interestingly, circular RNAs (circRNAs), defined as crucial cancer regulators, decreased the expression of FOXM1 and promoted the expression of CENPA and CENPB to facilitate cell cycle progression." (PMID 36741311, 2023). "In addition, CENPA also appears as the main regulator of MKI67 (Ki-67), a common prognostic and proliferation marker widely used in cancer histopathology." (PMID 36358698, 2022). "Numerous studies have identified the aberrant expression of CENPA gene in cancers, but related data in PRCC have not been reported yet." (PMID 36163007, 2022). "With regard to diseases or cancer, it is currently thought that CENPA functions downstream of the pathway or axis rather than upstream." (PMID 34627268, 2021). "Expression of CENPA, FOXM1, and MYBL2 did not appear to be very strongly associated with age, sex, or cancer stage." (PMID 32925947, 2020). "When we compared our LUAD data with that of a similar analysis of BRCA, CENPA, FOXM1, and MYBL2 were also found to be activated, particularly in basal-subtype tumors, supporting the idea that these factors work together in certain cancer subtypes." (PMID 32925947, 2020). "CENPA is a genomic marker for centromere activity and human diseases, including cancer, but it is not established as an important gene for lung AC diagnostics and prognosis." (PMID 22369099, 2011). "CenpA, dad1, BI-1 and MIF are also overexpressed in human cancers." (PMID 17311107, 2007). "The expression analysis supported this hypothesis, showing that cancer cells indeed express higher levels of CENPA compared to non-cancerous cells." (PMID 39820192, 2025). "In colonial cancer, CENPA was reported to recruit histone acetyltransferase general control of amino acid synthesis (GCN)-5 to the promoter region of the karyopherin α2 subunit gene (KPNA2), thereby boosting KPNα2 activation, which facilitated proliferation and glycolysis in cancer cells." (PMID 39820192, 2025). "Additionally, our study revealed that NTMT1, which methylates the α-N-terminal amines of proteins [e.g., RCC1 (regulator of chromosome condensation 1), CENPA (centromere protein A), and DDB2 (damage specific DNA binding protein 2)], likely possesses cancer-promoting roles." (PMID 34285249, 2021). "Such correlation is also found in other types of human cancer, such as cancers from lung, ovary, prostate (data not shown), suggesting that compatible mRNA levels of HJURP and CENPA might be required for tumor progression." (PMID 20211017, 2010).
tumor (90 papers, 2004 to 2025). "Single-cell analysis revealed that CENPA-high subpopulations were enriched in proliferative tumor cells and were associated with an immunosuppressive tumor microenvironment." (PMID 41425594, 2025). "Our present study attempts to shed light on the implication of DAXX, HJURP and CENPA in the carcinogenesis of UMs and associate their immunohistochemical expression in tumor tissues with patients’ clinicopathological parameters and prognosis." (PMID 39200236, 2024). "HJURP and CENPA mRNA overexpression exhibited strong association with tumor epithelioid histology and was linked to worse prognosis." (PMID 39200236, 2024). "Subsequently, a prognostic risk score for all tumor samples was calculated using the formula: prognostic risk score = expression level of G6PD*(0.15) + expression level of CENPA*(0.075) + expression level of STC2*(0.018) + expression level of PFKFB4*(0.053)." (PMID 35938165, 2022). "As one of the histone H3 variants, CENPA acts crucially in mitosis and contributes to tumor occurrence and development." (PMID 34627268, 2021). "CENPA overexpression may cause chromosome missegregation, promote genomic instability, and ultimately promote tumor progression." (PMID 40251374, 2025). "Moreover, a significant correlation was found between CENPA expression and tumor stemness and tumor mutational burden based on the TCGA-BLCA database." (PMID 40804263, 2025). "To test the first hypothesis, we analyzed the correlation between CENPA expression and two mutation indicators: tumor mutation burden (TMB) and microsatellite instability (MSI)." (PMID 39820192, 2025). "Furthermore, after treatment with CHIR‐99021, we found that it partially reversed the effects of CENPA knockdown on cells, improving the reduced tumour proliferation caused by CENPA knockdown (p < 0.05)." (PMID 39620895, 2024). "We further aim to investigate whether there are potential anti-tumor drugs associated with CENPA." (PMID 39456925, 2024). "CENPA and MYBL2 have been implicated in cell cycle regulation and transcriptional control and have been linked to aggressive tumor growth." (PMID 41402347, 2025). "TPX2, CENPA and RRM2 showed the strongest association with elevated PSA levels, particularly in the > 4 ng/mL group, indicative of higher tumor burden and poorer prognosis." (PMID 41402347, 2025). "While overexpression of CENPA increases target gene transcription and accelerates cell proliferation, CENPA knockdown inhibits tumor development." (PMID 39968078, 2025). "The authors observed that overexpression of CENPA increased proliferation and colony formation, thereby enhancing the oncogenic effect of this protein, and that CENPA knockdown dramatically suppressed tumor development." (PMID 39968078, 2025). "Several CENP genes, including CENPA, CENPF, and CENPU, are dysregulated in BC and are associated with patient prognosis, underscoring their relevance in tumor biology." (PMID 41425594, 2025). "Analysis of paired normal tumor transcriptome from 101 datasets showed that overexpression of CENPA is a common feature in over 44% of human cancers." (PMID 40804263, 2025). "On the other hand, CENPA, as a core centromeric protein, primarily affects tumor immunity indirectly by inducing chromosomal instability." (PMID 41589308, 2025). "The fact that CENPA affects both processes at the cellular level suggests it has the potential to impact on tumor immunity." (PMID 41589308, 2025). "Colony formation assay revealed a significant difference in colony formation of cells silencing CENPA expression compared to the control group, suggesting that CENPA affects tumor growth." (PMID 41589308, 2025). "We found that CENPA and IGF2BP3 were most closely associated with prognosis and tumor immunity in KIRC, so we explored the function and mechanism of CENPA and IGF2BP3 in KIRC." (PMID 41589308, 2025).